CTLA4 (cytotoxic T-lymphocyte associated protein 4)
Description:
Inhibitory receptor acting as a major negative regulator of T-cell responses. Acts as a decoy receptor: the affinity of CTLA4 for its natural B7 family ligands, CD80 and CD86, is considerably stronger than the affinity of their cognate stimulatory coreceptor CD28.
Synonyms: CTLA-4; CD152; CD; GSE; ALPS5; CELIAC3; GRD4; IDDM12
Tractability: Small molecule: a structure with a bound ligand is known. Antibody: an approved drug acts on it; UniProt places it where antibodies can reach, with high confidence; its Gene Ontology location is reachable by antibodies, with high confidence; UniProt predicts a signal peptide or a membrane-spanning region.
Target class: Surface antigen
Safety:
Unwanted effects reported when the protein is acted on. In parentheses: how it was acted on, where the effect was seen, and who reports it.
a hypersensitivity reaction (source: ClinPGx)
earlier onset of bortezomib-induced peripheral neuropathy (source: ClinPGx)
gingival overgrowth (source: ClinPGx)
later onset of bortezomib-induced peripheral neuropathy (source: ClinPGx)
paradoxical psoriasiform reactions (source: ClinPGx)
Gene: Protein-coding gene on chromosome 2 (203,853,888 to 203,873,965, forward strand). Ensembl gene ENSG00000163599.
Subcellular location: Cell membrane
Pathways (Reactome):
Immune System: Co-inhibition by CTLA4; Co-stimulation by CD28
Gene expression (Transcription): RUNX1 and FOXP3 control the development of regulatory T lymphocytes (Tregs)
Gene Ontology:
Molecular function: protein binding; receptor decoy activity
Biological process: B cell receptor signaling pathway; DNA damage response; negative regulation of B cell proliferation; negative regulation of regulatory T cell differentiation; negative regulation of T cell activation; negative regulation of T cell receptor signaling pathway; positive regulation of apoptotic process; immune response; T cell receptor signaling pathway; negative regulation of T cell proliferation; regulation of T cell proliferation
Cellular component: clathrin-coated endocytic vesicle; external side of plasma membrane; Golgi apparatus; perinuclear region of cytoplasm; plasma membrane; protein complex involved in cell adhesion; membrane
Genetic constraint (gnomAD): Loss-of-function variants: 0 observed, 14.15 expected, observed/expected ratio (o/e) 0, 90% interval 0 to 0.21. The upper end of that interval is the gene's LOEUF score, 0.21, which puts it in group 1 of 6, group 1 being the genes least tolerant of losing a copy. Missense variants: 142 observed, 228.51 expected, observed/expected ratio (o/e) 0.62, 90% interval 0.54 to 0.71. Synonymous variants: 80 observed, 90.06 expected, observed/expected ratio (o/e) 0.89, 90% interval 0.74 to 1.07.
Gene-disease validity (ClinGen):
ClinGen rates the evidence that CTLA4 causes each of these diseases.
autoimmune lymphoproliferative syndrome due to CTLA4 haploinsufficiency (autosomal dominant): Definitive. A somatic mutation in the CTLA4 gene resulting in only a single functional gene.
Homologues: Orthologues: chimpanzee CTLA4 (100% identical), macaque CTLA4 (97% identical), dog CTLA4 (87% identical), pig CTLA4 (85% identical), rabbit CTLA4 (85% identical), guinea pig CTLA4 (79% identical), rat Ctla4 (75% identical), mouse Ctla4 (75% identical), tropical clawed frog ctla4 (34% identical). Paralogues in human: CD28 (27% identical).
Diseases named in the same sentence as CTLA4 in open-access papers:
CTLA4 is named in the same sentence as 822 diseases in open-access papers, as found by Europe PMC text mining. Sharing a sentence is not in itself a finding about the gene and the disease. The quoted sentences say what the papers report.
melanoma (3,153 papers, 2007 to 2026). A malignant, usually aggressive tumor composed of atypical, neoplastic melanocytes. "Even greater progress has been made in melanoma: Neoadjuvant PD-1 blockade, both alone and in combination with a CTLA-4 blocker, significantly reduces the risk of recurrence." (PMID 41580899, 2026). "Stratifying melanomas by TLS gene expression signature revealed that tumors with high TLS levels were associated with significantly increased survival following CTLA-4 blockade." (PMID 40940789, 2025). "In the CTLA-4 inhibitor treatment group, both all-grade and serious-grade nausea, rash, and appetite loss were more prevalent in prostate cancer patients than in melanoma patients." (PMID 39866435, 2025). "Comparing the two main agents when treating melanoma with ICIs, anti-CTLA-4 inhibitors are more likely to cause hypophysitis than PD-L1 inhibitors." (PMID 41375894, 2025). "The bacterial species B. fragilis and B. thetaiotaomicron have been associated with improved antitumor effects of anti-cytotoxic T-lymphocyte-associated antigen-4 (CTLA-4) therapy in melanoma patients." (PMID 40927726, 2025). "First approved in 2011 for targeting anti-cytotoxic T lymphocyte-associated protein 4 (anti-CTLA-4) in advanced melanoma, Ipilimumab was soon followed in 2014 by two anti-programmed cell death protein 1 (anti-PD-1) agents, Pembrolizumab and Nivolumab." (PMID 40134430, 2025). "Two studies have reported that lower baseline serum IL-6 levels were associated with the development of irAEs in melanoma patients treated with anti-CTLA-4 therapy." (PMID 40632185, 2025). "Both imPERCIST5 and PERCIMT are immune-modified response criteria that were initially studied in cohorts of melanoma patients treated with the anti-cytotoxic T-lymphocyte associated protein 4 (CTLA4) agent Ipilimumab." (PMID 40430520, 2025). "In melanoma, the efficacy of cytotoxic T-lymphocyte associated protein 4 (CTLA-4) blockade has been associated with an increased abundance of Bacteroides thetaiotaomicron and Bacteroides fragilis, which enhance Th1-mediated immune responses." (PMID 40227812, 2025). "Combining HSP90 inhibition and anti-CTLA-4 monotherapy efficiently reduced melanoma tumor size, which was associated with an increase in the expression of IFN-γ-regulated genes." (PMID 40108693, 2025). "More importantly, our study revealed that patients with elevated PAN3-AS1 levels were linked to inferior outcomes when PD1 and CTLA4 inhibitors were used to treat melanoma patients." (PMID 41502505, 2025). "This stable HRQL profile for nivolumab aligns with clinical experience in patients with advanced melanoma that PD-1 inhibitors cause fewer severe adverse effects than CTLA-4 blockade, allowing patients to carry on with normal activities to a greater extent." (PMID 41463169, 2025). "A pooled analysis of six clinical trials involving 573 patients with high-risk resectable melanoma compared the safety and efficacy of neoadjuvant combination therapy with anti-PD-1 and anti-CTLA-4 inhibitors to anti-PD-1 monotherapy." (PMID 40004731, 2025). "Here, using whole-exome sequences (WESs) from pre and post melanomas and patient-matched normal tissues, we identified and functionalized somatic, recurrent mutations specific to relapsing or recurrent melanomas after anti-PD-1 ± anti-CTLA-4 therapy." (PMID 41175874, 2025). "In melanomas with brain metastases the expression of cytotoxic T-lymphocyte-associated protein 4 (CTLA-4; CD152) detected in the immune cell (CD45+) ROIs was higher than in tumors without metastases or metastases at other sites." (PMID 40621453, 2025). "Emerging clinical observations are reporting neurological complications associated with treatment using anti-CTLA-4 and anti-PD-1 in patients with melanoma, lung cancers, and Merkel-cell carcinoma at five weeks post-therapy." (PMID 40313772, 2025).
melanoma (continued). "A study from the United States identified malignant melanoma and ICPi anti-CTLA-4 monotherapy as risk factors for an ischemic stroke, while patients with neck and head cancers had lower risk of ischemic stroke." (PMID 40168398, 2025). "It was in 2011, with the FDA’s approval of ipilimumab, a cytotoxic T-lymphocyte associated protein 4 (CTLA-4)-targeting immune checkpoint inhibitor (ICI) for the treatment of melanoma that cancer immunotherapy entered a renaissance." (PMID 40725619, 2025). "Immune checkpoint inhibitors (ICI) targeting programmed cell death 1 (PD-1) or cytotoxic T lymphocyte-associated protein 4 (CTLA-4) are standard of care for advanced-stage melanoma and have considerably improved patient survival." (PMID 40522918, 2025). "The two main checkpoints currently targeted in melanoma are cytotoxic-T-lymphocyte-associated protein 4 (CTLA-4), programmed death-protein 1 (PD-1), and programmed death-ligand 1 (PD-L1)." (PMID 40361330, 2025). "Another investigation revealed that CTLA4 rs4553808 was associated with an increased risk of autoimmune disease including endocrinopathy in melanoma patients treated with ipilimumab." (PMID 41153639, 2025). "Retseck found that diminished baseline concentrations of circulating CD39+ Tregs were markedly linked to improved relapse‐free survival after anti‐CTLA‐4 treatment in melanoma patients." (PMID 40000397, 2025). "Blockade of Cytotoxic T-lymphocyte-associated protein 4 (CTLA-4) and Programmed Cell Death Protein 1 (PD-1) significantly improves progression-free survival in patients with cancers, including melanoma." (PMID 40605058, 2025). "Despite these limitations, the study provides the largest and most comprehensive risk analysis to date of neurologic irAEs in melanoma patients treated with combination anti-PD-1/CTLA-4 immunotherapy versus anti-PD-1 monotherapy." (PMID 40351833, 2025). "The pattern of DNA methylation change in the promoter regions of CTLA4 is associated with the immunotherapy response and progression-free survival in patients with melanoma." (PMID 40864319, 2025). "ICIs were first introduced in 2011 with the development of ipilimumab, an anti-cytotoxic T-lymphocyte-associated antigen-4 (CTLA-4) monoclonal antibody for melanoma." (PMID 40723228, 2025). "On the other hand, analyzing melanoma and adrenocortical carcinoma cohorts with the same risk score, mRNAsi showed an inverse correlation with CTLA-4 expression." (PMID 41233805, 2025). "Melanoma patients receiving combination anti-PD-1/CTLA-4 immunotherapy have greater long-term risk of n-irAEs than patients receiving anti-PD-1 monotherapy." (PMID 40351833, 2025). "In melanoma, various gut bacterial species affect the body’s immune responses to anti-cytotoxic T-lymphocyte associated protein 4 (CTLA4) and anti-programmed cell death protein 1 (PD-1) therapy." (PMID 39578323, 2025). "When comparing TRAEs associated with anti-PD-1 monotherapy and anti-CTLA-4 monotherapy in melanoma patients, it becomes evident that the overall incidence of all-grade adverse effects is higher among anti-PD-1 patients." (PMID 39866435, 2025). "The protein encoded by CTLA4 is mainly expressed in tumor cells and a subset of tumor-infiltrating immune cells in melanoma." (PMID 40864319, 2025). "We report here three melanoma studies evaluating blood TCR repertoire shifts after anti-CTLA-4 therapy and their association with patient response." (PMID 41244934, 2025). "We present a 48-year-old female with recurrent malignant melanoma who underwent 23 cycles of nivolumab, a PD-1 inhibitor, and 11 cycles of combined cytotoxic T lymphocyte associated antigen 4 (CTLA-4) inhibitor and PD-1 inhibitor ipilimumab-nivolumab." (PMID 39935494, 2025). "Clinically, increased circulating myeloid-derived suppressor cells (MDSCs) has been associated with poor response to anti-CTLA4 therapies in melanoma patients." (PMID 41256311, 2025).
melanoma (continued). "Knockdown of XBP1 enhances immunotherapeutic efficacy of antibodies blocking programmed death protein 1 (PD1) and cytotoxic T lymphocyte-associated antigen 4 (CTLA4) in melanoma." (PMID 41050076, 2025). "In the ongoing S1404 study (NCT01274338, n = 1673), a direct comparison of the efficacy of high-dose Intron-A and ipilimumab (anti-CTLA-4) in adjuvant therapy for patients with high-risk melanoma is being conducted." (PMID 41373826, 2025). "In recent years, the immunologic origin of melanoma has led to the discovery of antibodies directed against specific targets such as anti-programmed cell death 1 (PD-1) and anti-cytotoxic T-lymphocyte-associated protein 4 (CTLA-4)." (PMID 38571962, 2024). "Immune checkpoint inhibitors, including antibodies against cytotoxic T-lymphocyte associated protein 4 (CTLA-4) and programmed cell death protein 1 (PD-1), have shown promise in cancer types such as melanoma, NSCLC, and head and neck cancers." (PMID 39558957, 2024). "The advent of immune checkpoint inhibitors (ICI) targeting cytotoxic T-lymphocyte-associated antigen 4 (CTLA-4) and programmed death 1 (PD-1) has transformed the management of advanced melanoma." (PMID 39001417, 2024). "For melanoma patients with brain metastases, the common immune checkpoint inhibitors used for monotherapy are PD-1/PD-L1 and cytotoxic T lymphocyte-associated protein 4 (CTLA-4)." (PMID 39935851, 2024). "The ICB therapy for melanoma primarily targets cytotoxic T-lymphocyte-associated protein 4 (CTLA-4) and programmed cell death protein 1 (PD-1)." (PMID 38594730, 2024). "CPIs for melanoma treatment primarily targeted two main checkpoint proteins: cytotoxic T-lymphocyte-associated antigen 4 (CTLA-4) and programmed cell death protein 1 (PD-1)." (PMID 38399429, 2024). "For example, therapeutic regimens targeting cytotoxic T-lymphocyte-associated protein 4 (CTLA4) and programmed death 1 (PD-1) increase tumor regression rates from less than 10% to nearly 50% in patients with advanced melanoma." (PMID 38982511, 2024). "A retrospective evaluation of a melanoma patient registry reveals that anti-CTLA4 reduces lymphedema risk; in parallel, anti-CTLA4 reduces edema and improves lymphatic function in a mouse-tail lymphedema model." (PMID 39737964, 2024). "Treatment with anti-PD-1 and/or anti-CTLA-4 was also associated with low testosterone levels in 34 of 49 (69%) men with melanoma." (PMID 38539511, 2024). "The U.S. Food and Drug Administration (FDA) first approved an immune checkpoint inhibitor (ICI) therapy for melanoma in 2011, ipilimumab, which is an antibody that targets the cytotoxic T-lymphocyte-associated protein 4 (CTLA-4)." (PMID 39610923, 2024). "Preclinical studies demonstrated that anti-CTLA-4 treatment was associated with the expansion of IFNγ+ICOS+CD4+ T cells in melanoma and other solid tumors." (PMID 39247203, 2024). "In 2011, Ipilimumab was first approved to treat advanced melanoma patients by blocking the action of cytotoxic T-lymphocyte-associated antigen 4 (CTLA-4)." (PMID 39337333, 2024). "Immunotherapy, particularly immune checkpoint inhibitors (ICIs) targeting programmed cell death protein 1 (PD-1) and cytotoxic T-lymphocyte-associated antigen 4 (CTLA-4), has revolutionized the treatment landscape of melanoma." (PMID 39061208, 2024). "Immune checkpoint inhibition (ICI) targeting the programmed cell death protein 1 (PD-1), programmed cell death protein ligand 1 (PD-L1), and cytotoxic T-lymphocyte-associated protein 4 (CTLA-4) has dramatically improved outcomes in melanoma patients." (PMID 38539560, 2024). "Our data reveal that in patients with melanoma who received anti–PD-1/–CTLA-4 blockade, PRKDC mutations were associated with a higher TMB, neoantigen loads, and enhanced responses." (PMID 39436696, 2024). "Melanoma tumors with loss of IFNGR signaling are resistant to CTLA-4 ICB therapy, probably due to the attenuated suppression of tumor cell proliferation and apoptosis." (PMID 38982116, 2024).
melanoma (continued). "In the B16F10 melanoma model, directing anti-CTLA4 and anti-PD-1 treatment to the TDLN reduces the risk of immune-related adverse events, reduces distant metastases and recurrence, and enhances the anti-cancer T cell repertoire." (PMID 39211044, 2024). "Out of the 13,568 individuals diagnosed with malignant melanoma, 145 individuals underwent PD-1i therapy, while another 212 received treatment with cytotoxic T-lymphocyte-associated protein-4 inhibitor (CTLA-4i)." (PMID 38482205, 2024). "Tumor-associated AAbs have shown promise in CTLA-4 and PD-1 monoclonal antibody therapies for melanoma and lung cancer, exemplified by the survival association of NY-ESO-1 AAb in these patients." (PMID 38513890, 2024). "This study aimed to evaluate the frequency of HPD and its associated risk factors in patients with advanced melanoma receiving anti-PD-1 monotherapy or anti-PD-1 combined with anti-CTLA-4 therapy." (PMID 39451776, 2024). "Inhibitors of programmed death 1 (PD-1), programmed death ligand 1 (PD-L1), and cytotoxic T lymphocyte-associated antigen 4 (CTLA4) have demonstrated antitumor effects in malignant melanoma and non-small-cell lung cancer." (PMID 38655053, 2024). "Other studies recommend that anti-PD-1 is associated with better overall survival than anti-CTLA4 in both advanced or recurrent melanoma of the cervix." (PMID 38920558, 2024). "This research offers significant findings on the impact of a treatment combination using anti-CTLA-4 and anti-PD-1 antibodies on vascular and systemic inflammation caused by myeloid cells in patients with melanoma, as well as in mice with hyperlipidemia." (PMID 38482205, 2024). "The highest risk and incidence occurred in patients with melanoma receiving a combination of anti-CTLA4 and anti-PD1, 28.4% and 38.1 per 1,000 person-months, respectively." (PMID 37727807, 2023). "In the immune microenvironment of melanoma, cytotoxic T-lymphocyte-associated protein-4 and programmed cell death protein-1 on the T-cell membrane bind to ligands on dendritic cells, thereby attenuating tumor immunity and leading to tumor progression." (PMID 37305390, 2023). "Adjuvant treatment with immune checkpoint inhibitors like PD1-antibodies (ICI) ± CTLA4-antibodies (cICI) or targeted therapy with BRAF/MEK inhibitors (TT) in high-risk melanoma patients demonstrate a significant improvement in disease-free survival (DFS)." (PMID 37405475, 2023). "Of note, we validated the role of RAC1, an ERG, in modulating the behavior of melanoma cells and regulating the expression of programmed cell death-1 (PD-1)/programmed death-ligand 1 (PD-L1) and cytotoxic T-lymphocyte-associated antigen 4 (CTLA4) in vitro." (PMID 37217516, 2023). "Association between survival, log CTLA4 cut-point, melanoma stage, age, and sex by multivariable Cox PH model for US patients (n = 263, 65 events), primary melanoma (n = 165, 10 events), and metastatic melanoma (n = 98, 55 events)." (PMID 37197667, 2023). "The first evidence of this association was noticed in melanoma mouse models, where it was found that the gut microbiota modulates the response to anti-CTLA-4 and anti-PD-L1 antibody therapies." (PMID 37190279, 2023). "Other studies suggest that anti-PD-1 is associated with better overall survival compared to anti-CTLA4 in advanced or recurrent melanoma of the female reproductive tract." (PMID 36979090, 2023). "Association between survival, log CTLA4 cut-point, melanoma stage, age, and sex by multivariable Cox PH model for AUS patients (n = 170, 34 events), primary melanoma (n = 122, 9 events), and metastatic melanoma (n = 48, 25 events)." (PMID 37197667, 2023). "Cytotoxic T lymphocyte-associated protein 4 (CTLA4)-specific immune-checkpoint blockers have been approved for melanoma treatment and derepress autophagic responses of DCs in the Treg-infiltrated TME." (PMID 36814780, 2023).